NOTCH1 (notch receptor 1)
Diseases named in the same sentence as NOTCH1 in open-access papers (continued):
Sharing a sentence is not in itself a finding about the gene and the disease.
oral squamous cell carcinoma (25 papers, 2012 to 2026). "NOTCH1 is associated with various tumors, including oral squamous cell carcinoma (OSCC), with a complex role depending on cellular contexts." (PMID 41752081, 2026). "In conclusion, our findings indicate that Notch1 mutation is a potential therapeutic target for enhancing immune recognition in oral squamous cell carcinoma." (PMID 41026775, 2025). "Clinicopathological parameters of 12 patients with oral squamous cell carcinoma (OSCC) according to Notch1 mutation." (PMID 41026775, 2025). "We previously performed whole exome sequencing of a panel of HPV-negative keratinocyte lines derived from oral squamous cell carcinomas (OSCCs), and identified NOTCH1 mutations in several of the lines." (PMID 31827722, 2019). "Inactivating mutations in the EGF-like ligand binding domain of NOTCH1 are a prominent feature of the mutational landscape of oral squamous cell carcinoma (OSCC)." (PMID 31827722, 2019). "Therefore, it is clinically important to investigate the effects of Notch1 mutations on antitumor immunity in oral squamous cell carcinoma (OSCC), a subset of HNSCC." (PMID 41026775, 2025). "Therefore, other studies report that NOTCH1 is a tumor suppressor gene that finds gene mutations in 54% of oral squamous cell carcinoma and 60% of preneoplastic lesions in Chinese patients." (PMID 37008245, 2023). "In addition to TMB, NOTCH1 mutations are also known to be oncogenic, and in a study focusing on oral squamous cell carcinoma and HNSCC cell lines, patients with tumors carrying NOTCH1 mutation had significantly poorer survival outcomes." (PMID 35911687, 2022). "Interestingly, a recent study showed that mutation of NOTCH1 in oral squamous cell carcinoma occurs in 15% of the Caucasian population, whereas in the Asian population the rate of NOTCH1 mutations was about 50%." (PMID 31443481, 2019). "Overview of clinicopathological parameters, somatic Notch1 mutations, PD‐L1 protein expression by combined positive score (CPS), and tumor‐infiltrating CD8+ T cells in 12 patients with oral squamous cell carcinoma (OSCC)." (PMID 41026775, 2025). "The aim of this study was to investigate the clinical and prognostic significance of the NOTCH1 pathway in oral squamous cell carcinoma (OSCC)." (PMID 41009728, 2025). "The expression of Notch1 is reportedly up-regulated in oral squamous cell carcinoma, correlating with T-stage and clinical staging." (PMID 38866828, 2024). "On the contrary, activation of the NOTCH1 signaling pathway can promote the progression of oral squamous cell carcinoma (OSCC)." (PMID 37008245, 2023). "The strong immunoexpression of Notch1 can contribute to identification of patients with poorly differentiated oral squamous cell carcinoma, who have perineural infiltration or lymph node metastasis." (PMID 33854547, 2021). "Statistically significant associations were observed between the strong immunoexpression of Notch1 in poorly differentiated oral squamous cell carcinoma with perineural infiltration (p = 0.011) and lymph node involvement (pN+) (p = 0.034)." (PMID 33854547, 2021). "The expression of ALDH1 and Notch1 in 63 patients with well and poorly differentiated oral squamous cell carcinomas and their subtypes, verrucous carcinoma and basaloid squamous cell carcinoma, was evaluated by immunohistochemistry." (PMID 33854547, 2021). "Strong ALDH1 and Notch1 expression was observed in 16 (25.4%) and 27 (42.9%) oral squamous cell carcinomas including their subtypes, respectively." (PMID 33854547, 2021). "The present study aimed to investigate the clinical significance and prognostic value of the immunoexpression of cancer stem cell markers, ALDH1 and Notch1, in subtypes of oral squamous cell carcinoma." (PMID 33854547, 2021). "NOTCH1 was also found to be crucial for the maintenance of stemness in oral squamous cell carcinoma (OSCC)." (PMID 34944837, 2021).
oral squamous cell carcinoma (continued). "Mutations in NOTCH1 were strongly associated with shorter overall (OS) and disease-free survival (DFS) (p = 0.004 and p = 0.001, respectively) in Chinese oral squamous cell carcinoma (OSCC) patients compared to patients with wt NOTCH1." (PMID 33322834, 2020). "Reduced expression of NOTCH1 has been detected by immunohistochemistry not only in oral squamous cell carcinoma but also in oral epithelial dysplasia, suggesting that deregulation of NOTCH1 is an early event in the disease." (PMID 30744164, 2019). "Of late, PI3K inhibitors are under investigation as targeted anticancer agents against a variety of cancers, including oral squamous cell carcinoma, and they may provide a synergistic strategy with NOTCH1-directed therapy." (PMID 40672020, 2025). "This research evaluated the expression of NOTCH1 across two types of oral cancer (oral squamous cell carcinoma {OSCC} versus mucoepidermoid carcinoma {MEC}) and healthy controls to observe its correlation with immune suppression and patterns of disease progression." (PMID 40672020, 2025). "NOTCH1 plays an important role in oral squamous cell carcinoma angiogenesis." (PMID 38650654, 2024). "The role of Notch1 signaling in oral squamous cell carcinoma (OSCC) remains poorly understood." (PMID 37859809, 2023). "The Notch1, a protein of the Notch signaling pathway, plays a fundamental role in several cellular processes such as proliferation and angiogenesis and in the epithelial-mesenchymal transition process, and its expression is well established in oral squamous cell carcinoma (OSCC)." (PMID 33854547, 2021). "In oral squamous cell carcinoma (OSCC), Notch1 has an orchestrating role in the maintenance of undifferentiation, and blockage of the NOTCH1-Hes1 axis inhibits the CSC phenotype." (PMID 32796631, 2020). "Additionally, in oral squamous cell carcinoma (OSCC), NOTCH1 signalling has also been convincingly shown to promote metastasis, possibly via the support of EMT." (PMID 34944837, 2021). "Moreover, curcumin mediated inhibition of Notch1 activation also led to the downregulation of NF-κB and its target genes, including Bcl-2, cyclin D1, vascular endothelial growth factor (VEGF), and matrix metalloproteinase-9 (MMP-9) in oral squamous cell carcinoma cells." (PMID 24024180, 2013).
skin cancer (25 papers, 2005 to 2025). "Additional loss of Notch1 (LNPT mice) greatly accelerated skin tumour formation (median survival =169 days, p < 0.001 [log rank Mantel-Cox test, chi square 25.13, df 1])." (PMID 37626054, 2023). "This is based on the observation that the frequency of NOTCH1 mutations decreases in esophageal and skin cancers, relative to physiologically normal epithelial tissues." (PMID 33435458, 2021). "Mice with epidermal loss of Notch1 as well as Presenilin-deficient mice develop epidermal hyperplasia and skin cancers." (PMID 21042537, 2010). "In such cells, Notch signaling induces cell growth arrest and differentiation (deletion of Notch1 in murine epidermis causes epidermal hyperplasia and skin carcinoma)." (PMID 19828018, 2009). "Skin metastases that harbor NOTCH1 mutations were classified as skin cancer at a higher rate (18% vs 5%, p = 0.052), but the effect was primarily driven by differences in subtype prevalence between local tumors and skin metastases and was not significant after controlling for this (p = 0.78)." (PMID 32374727, 2020). "The upregulation of the Wnt/beta-catenin pathway, which may result from Notch1 loss of function, facilitates skin tumor development and promotion, and is at least partly dependent on p21WAP/Cip1." (PMID 32331425, 2020). "We observed that SGK3 depletion resulted in elevated N1 TM, N1ICD levels, indicating that SGK3 contributes to the destabilization of NOTCH1 in skin cancer cells." (PMID 39663000, 2025). "Our findings on the involvement of NOTCH1 in skin cancer development are consistent with those in the current literature." (PMID 39063983, 2024). "Recent studies have highlighted the roles of various oncogenes in skin cancer, including NOTCH1 and FGFR2." (PMID 39063983, 2024). "In vivo mouse studies show that Notch1 deletion, a mutation that occurs early in CSCC, results in the development of skin tumors and facilitation of chemically-induced skin carcinogenesis." (PMID 32331425, 2020). "In conditional Notch1 knockout mice, an increased incidence in skin cancers has been reported, and the incidence of papilloma formation in Notch1 null skin was markedly increased by exposure to chemical carcinogens plus phorbol ester." (PMID 26176534, 2015). "Such different activities of Notch1 in skin cancer are probably determined by its interaction with the downstream β-catenin target." (PMID 19828018, 2009). "In murine skin carcinoma, β-catenin is functional activated by Notch1 signaling and mediates tumor-suppressive effects." (PMID 19828018, 2009). "Some studies report that Notch1 activation leads to impaired proliferation of keratinocytes, whereas a defect in Notch1 signaling in keratinocytes leads to excessive epidermal proliferation in mice that may even result in skin tumors." (PMID 36891783, 2023). "For instance, a study has reported that in skin cancer Notch-1 plays an oncosuppressive role." (PMID 35686109, 2022). "Further analysis revealed that loss of Notch1 but not Notch2 is critical for skin tumor development." (PMID 21042537, 2010). "However, double Notch1 and Notch2 knockout mice (Pdx1-Cre;Kras;N1ko;N2ko) featured an accelerated skin tumor formation suggesting an essential role of Notch1 ablation in epidermal lesion development and a promoting role of Notch2 deletion." (PMID 21042537, 2010). "Therefore, NOTCH1 is a promising target for personalized and targeted therapies for skin cancer." (PMID 39063983, 2024).
skin cancer (continued). "Importantly, sulforaphane has been shown to attenuate a number of UVR-induced DMRs, e.g. within Notch1 and Smad6, in the mouse skin and reduce the incidence and multiplicity of skin cancer, in agreement with our early observations using broccoli extracts as delivery vehicles for sulforaphane." (PMID 34000624, 2021). "The versatile effects of Notch1 signaling on cell differentiation, proliferation, survival, and tumorigenesis may easily explain why Notch1 plays different roles in various types of skin cancers." (PMID 19828018, 2009). "Because SGK3 appears to negatively regulate NOTCH1 levels, we depleted it in SCC022 skin cancer cells in which low levels of NOTCH1 promote tumorigenesis." (PMID 39663000, 2025). "The primary aim of this research was to evaluate the activation of NOTCH1 and FGFR2 oncogenes in inducing skin cancer in FVB/N mice through a stepwise chemical process." (PMID 39063983, 2024). "This study aims to evaluate the activation of NOTCH1 and FGFR2 oncogenes in inducing skin cancer in FVB/N mice through a stepwise chemical process, providing new insights into their involvement in cSCC development." (PMID 39063983, 2024). "Future studies incorporating male mice would be essential to comprehensively understand any potential sex-specific differences in the activation of NOTCH1 and FGFR2 oncogenes and their role in skin cancer induction." (PMID 39063983, 2024). "In contrast to Notch1, RBP-Jk expression is frequently reduced in lymphoma, breast, brain, cervix, kidney, oral, lung, prostate and skin cancers." (PMID 30004402, 2018). "In addition, we found that there was a significant correlation between the expression of Notch1 and p-AKT in skin cancer tissues by using IHC." (PMID 32015216, 2020). "In our study, Pdx1-Cre;Kras;N1ko but not Pdx1-Cre;Kras;N2ko or Pdx1-Cre;Kras developed skin lesions which points to the importance of Notch1 but not Notch2 for skin tumor development." (PMID 21042537, 2010). "In skin cancer cells, LOXL2 is recruited by KLF transcription factor 4 (KLF4) to the notch receptor 1 (NOTCH1) promoter, where it decreases H3K4me3 levels, thereby impairing RNA polymerase II recruitment and inhibiting NOTCH1 transcription, thus repressing epidermal differentiation." (PMID 37762708, 2023). "Moreover, in skin cancer cells, LOXL2 collaborates with KLF4 in the NOTCH1 promoter, where it oxidizes H3K4me3, thereby impairing RNA polymerase II recruitment and inhibiting NOTCH1 transcription, repressing epidermal differentiation." (PMID 37298909, 2023). "Finally, SGK3 depletion leads to elevated NOTCH1 levels and elevated NOTCH1 target gene expression in skin cancer cells, suggesting that SGK3 might act as a negative regulator in contexts in which NOTCH1 is a tumor suppressor, such as during skin tumorigenesis." (PMID 39663000, 2025).
aortic valve calcification (24 papers, 2011 to 2025). "For example, it has been shown that some variants of the NOTCH1 gene are associated with aortic valve calcification." (PMID 39125885, 2024). "Mutations in the Notch1 gene have been shown to result in aortic valve calcification in both humans and animal models." (PMID 36005436, 2022). "During calcific aortic valve disease, DNA methylation in the H19 promoter is dysregulated, causing H19 to interfere with the expression of NOTCH1 to promote the osteogenesis process in the aortic valve." (PMID 34583640, 2021). "Together, these current findings reveal a crucial role of NOTCH1 in aortic valve calcification, while the underlying mechanisms remain an area of intensive investigation." (PMID 34239905, 2021). "Various cardiac disorders (BAV, aortic aneurysm, aortic coarctation), as well as the formation and progression of aortic valve calcification, were reported in correlation with NOTCH1 variants." (PMID 33829027, 2021). "The Notch homolog 1 translocation-associated (NOTCH1) pathway is also involved in aortic valve calcification." (PMID 32664529, 2020). "Epigenetic dysregulation of long noncoding RNA H19 was recently found to be associated with calcific aortic valve disease (CAVD) in humans by repressing NOTCH1 transcription." (PMID 31609547, 2019). "NOTCH1 has been linked to HLHS owing to its contribution to a Mendelian form of calcific aortic valve disease and the identification of pathogenic compound heterozygous NOTCH1 mutations in HLHS patients." (PMID 28521042, 2017). "Recently, disease modeling of GATA4 and TBX5 pathogenic variants in human iPSC-derived CM and iPSCs-derived EC from patients with bicuspid aortic valve and calcific aortic valve disease with NOTCH1 haploinsufficiency have predicted that CHD-linked GRN is sensitive to gene dosage." (PMID 35970860, 2022). "They used hiPSC (human-induced pluripotent stem cell)-derived ECs generated from two patients with nonsense mutations in NOTCH1 and related unaffected individual to investigate how NOTCH1 haploinsufficiency may cause aortic valve calcification." (PMID 29026447, 2017). "Our results suggest that the OPG/RANKL/RANK system might be directly influenced by genetic variants of NOTCH1 in aortic valve calcification." (PMID 28246602, 2017). "Conversely, the reduced NO production, as occurs in endothelial cell dysfunction or in eNOS knockout mice, can in turn inhibit Notch‐1 signaling in AVICs and favor aortic valve calcification." (PMID 35986504, 2022). "It has been proven that rhIL-37 shifts macrophage polarization from the pro-inflammatory M1 phenotype to the anti-inflammatory M2 phenotype by inhibiting the Notch1 and NF-kB pathways to suppress the progression of calcific aortic valve disease." (PMID 35935954, 2022). "For calcific aortic valve disease, a dysregulation of DNA methylation in the H19 promoter stimulates a more osteogenic phenotype by interfering with NOTCH1 expression." (PMID 34103071, 2021). "The NOTCH1 mutations are the first identified human genetic variants that cause congenital bicuspid aortic valve (BAV) and calcific aortic valve disease (CAVD)." (PMID 34239905, 2021). "Mutations in NOTCH1 are known to predispose individuals to BAV and aortic valve calcification." (PMID 39859493, 2025). "Calcific aortic valve disease (CAVD), the third most common form of CVD, is also linked to Notch1 mutations and as a result, the similar approach of targeting the normalization of core Notch1 pathway components can be used for therapeutic applications." (PMID 34677194, 2021). "Recent research further highlights MEIS2’s role in calcific aortic valve disease (CAVD), where its inhibition promotes osteoblastic transdifferentiation and reduces Notch1 and Twist1 expression, making MEIS2 a potential target for CAVD prevention." (PMID 39758840, 2024).
aortic valve calcification (continued). "Telomere shortening in Notch1 haploinsufficient mice (Notch1+/−mTRG1–3) elicit age-dependent tricuspid AVS and aortic valve calcification, however, early lethality is observed." (PMID 37187784, 2023).